UBA7 (ubiquitin like modifier activating enzyme 7)
Description:
Plays an essential role in antiviral immunity together with ISG15 by restricting the replication of many viruses including rabies virus, influenza virus, sindbis virus, rotavirus or human cytomegalovirus. For example, ISG15 modification of influenza A protein NS1 disrupts the association of the NS1 with importin-alpha leading to NS1 nuclear import inhibition. ISGylation of human cytomegalovirs protein UL26 regulates its stability and inhibits its activities to suppress NF-kappa-B signaling.
Synonyms: UBE1L; UBE2; D8; UBA1B; UBE7
Tractability: Small molecule: a structure with a bound ligand is known. PROTAC: UniProt records ubiquitination sites on it; ubiquitination databases record sites on it; its protein half-life has been measured; a small molecule that binds it is known.
Target class: Enzyme
Gene: Protein-coding gene on chromosome 3 (49,805,205 to 49,814,151, reverse strand). Ensembl gene ENSG00000182179.
Subcellular location: Cytoplasm; Nucleus
Subcellular location (Human Protein Atlas): Nucleoplasm; Vesicles; Cytosol
Pathways (Reactome):
Immune System: Antigen processing: Ubiquitination & Proteasome degradation; DDX58/IFIH1-mediated induction of interferon-alpha/beta; ISG15 antiviral mechanism; Modulation of host responses by IFN-stimulated genes; Negative regulators of DDX58/IFIH1 signaling
DNA Repair: Termination of translesion DNA synthesis
Disease: Dengue Virus Attachment and Entry
Gene Ontology:
Molecular function: ISG15 activating enzyme activity; protein binding; ubiquitin-like modifier activating enzyme activity
Biological process: innate immune response; ISG15-protein conjugation; DNA damage response; protein ubiquitination
Cellular component: cytoplasm; nucleus; cytosol; nucleoplasm
Genetic constraint (gnomAD): Loss-of-function variants: 88 observed, 119.01 expected, observed/expected ratio (o/e) 0.74, 90% interval 0.62 to 0.88. The upper end of that interval is the gene's LOEUF score, 0.88, which puts it in group 3 of 6, group 1 being the genes least tolerant of losing a copy. Missense variants: 1,092 observed, 1,307.3 expected, observed/expected ratio (o/e) 0.84, 90% interval 0.79 to 0.88. Synonymous variants: 459 observed, 531.3 expected, observed/expected ratio (o/e) 0.86, 90% interval 0.8 to 0.93.
Homologues: Orthologues: chimpanzee UBA7 (99% identical), macaque UBA7 (96% identical), pig UBA7 (82% identical), dog UBA7 (81% identical), rabbit UBA7 (78% identical), mouse Uba7 (73% identical), guinea pig UBA7 (72% identical), rat Uba7 (70% identical), zebrafish uba1 (45% identical), tropical clawed frog uba1 (44% identical), zebrafish uba7 (43% identical). Paralogues in human: UBA1 (46% identical), UBA6 (36% identical), UBA2 (15% identical), NAE1 (12% identical), UBA3 (11% identical), ATG7 (10% identical), SAE1 (10% identical), MOCS3 (10% identical), UBA5 (7% identical).
Diseases named in the same sentence as UBA7 in open-access papers:
UBA7 is named in the same sentence as 40 diseases in open-access papers, as found by Europe PMC text mining. Sharing a sentence is not in itself a finding about the gene and the disease. The quoted sentences say what the papers report.
lung carcinoma (14 papers, 2008 to 2025). "Intersection analysis identified core COPD–lung cancer genes (UBA7, ZDHH5, GMPPB, IREB2, PYGB), with emphysema‐specific IREB2 (lung) and PSMA4 (blood)." (PMID 41377765, 2025). "The E1 enzyme UBA7 (also named UBE1L) of the ISG15 covalent modification system is located on chromosome 3p21, and 3p21 is missing in lung cancer patients; thus, UBA7 is often lowly expressed in lung cancer." (PMID 36771004, 2023). "UBA7/ISG15 signaling axis has been a prime focus in lung cancer, and many studies show downregulation of UBA7 in lung and breast cancer." (PMID 35612714, 2022). "UBA7 strikes as an interesting candidate also because of the low expression levels detected in lung cancer cell lines and the location of the gene on 3p21, a region frequently deleted in lung carcinomas associated with tobacco smoking and asbestos-exposure." (PMID 19014429, 2008). "To assess the potential importance of UBA1 and/or UBA7 in asbestos-associated lung cancer or lung carcinomas in general we measured the protein levels in normal and tumour tissue samples of 12 lung cancer patients (data not shown)." (PMID 19014429, 2008). "For example, UBA7 targets key regulatory proteins such as cyclin D1 and PML-RARα for proteasomal degradation, suppressing the growth of human lung cancer cells." (PMID 40158006, 2025). "The high expression of UBA7 can target cyclinD1 and PML-RARα for proteasome degradation, thereby inhibiting the growth of lung cancer cells." (PMID 36771004, 2023). "The GAPDH-scaled protein expression levels of UBA1 and UBA7 were compared between the exposed and non-exposed lung cancer patients, separately for the normal and tumour tissue samples." (PMID 19014429, 2008).
viral infection (7 papers, 2011 to 2025). "Although ISG15 conjugation is strongly induced by viral infection, UBA7-deficient mice show no significant different from controls upon infection with vesicular stomatitis and lymphocytic choriomeningitis viral infections, suggesting redundancy within interferon signaling pathways." (PMID 40570956, 2025). "Among these, the expression of Mx1, Mx2, TRIM22, WARS, ISG15, ISG20, UBA7, DDX58, and OAS1-3 were up-regulated, representing an increased innate immune response against viral infections." (PMID 25883591, 2015).
breast carcinoma (5 papers, 2020 to 2025). "UBA7 serves as a potential biomarker for diagnostic and prognostic prediction in breast cancer." (PMID 33344241, 2020). "A less stringent suppression of UBA7 is also seen with MCF7 breast cancer cells, which also express high levels of USP18." (PMID 37756534, 2023). "A breast cancer model in a UBA7 KO mouse has also indicated a tumour suppressor function of ISGylation." (PMID 37756534, 2023). "Furthermore, breast cancer patients with low UBA7 expression levels were shown to have a poor prognosis and low overall survival." (PMID 36010616, 2022). "Most prior research on the UBA7/ISG15 signaling pathway in cancer has concentrated on lung and breast cancer and reported that UBA7 gene expression was downregulated." (PMID 40158006, 2025).
chronic lymphocytic leukemia (1 paper, 2025). "Importantly, the clinical relevance of this finding is underscored by the observation that low UBA7 gene expression was associated with poor overall survival in chronic lymphocytic leukemia (CLL), another hematological malignancy with frequent SF3B1 mutations." (PMID 40158006, 2025).
colon cancer (1 paper, 2023). "Here, we provide an acute example of this phenomenon, whereby the early expression of USP18, post-interferon treatment of HCT116 colon cancer cells is sufficient to fully suppress the expression of the ISG15 E1 enzyme, UBA7." (PMID 37756534, 2023).
tuberculous pleurisy (1 paper, 2021). "A total of eight possible biomarkers of tuberculous pleurisy were screened (RPL17, UBA7, NDUFB8, UQCRFS1, JUNB, PSMC4, PHPT1, and MAPK11)." (PMID 34925441, 2021).
infection (21 papers, 2011 to 2024). The state of being infected such as from the introduction of a foreign agent such as serum, vaccine, antigenic substance or organism. "In contrast, genes such as Abce1 and Ptpn11 were only upregulated following rpoB-H445Y Mtb infection, whereas Uba7 was upregulated only during wt Mtb infection." (PMID 38603763, 2024).
tumor (15 papers, 2008 to 2025). "Functional studies, including in vitro assays and in vivo models, are essential to confirm the involvement of UBA7 in ISGylation processes, immune evasion mechanisms, and tumor progression." (PMID 40158006, 2025). "In the SCC group, however, protein expression of both UBA1 and UBA7 were significantly lower in tumour than in the normal tissue, p = 0.02 and p = 0.01 (two-sided t-test), respectively." (PMID 19014429, 2008). "Furthermore, a similar association between low UBA7 gene expression and poor survival outcomes was observed across multiple tumor types in the TCGA database, highlighting the broader implications of UBA7 dysregulation in cancer biology." (PMID 40158006, 2025). "These experiments could elucidate the molecular pathways regulated by UBA7 and its interactions with other key players in tumor biology." (PMID 40158006, 2025). "According to our analysis of a rather small number of normal and tumour tissue samples the asbestos-related deregulation of ubiquitination seems neither to be caused by UBA1 nor UBA7." (PMID 19014429, 2008). "Moreover, evaluating UBA7’s functional relevance across diverse tumor types could reveal its broader implications as a pan-cancer target." (PMID 40158006, 2025). "The findings presented in this work are derived from comprehensive computational analyses, providing valuable insights into the dysregulation of UBA7 in MDS and its potential roles in tumor biology." (PMID 40158006, 2025). "Consistent with this notion, this study identifies a novel role for UBA7 in MDS, and potentially CLL, as a tumor suppressor subjected to downregulation through disruptions in alternative splicing." (PMID 40158006, 2025). "Hundreds of ISG genes have been identified, and they act either as tumor drivers, such as ADAR1, or tumor repressors, such as UBA7." (PMID 36458816, 2022). "Namely, the protein levels of UBA1 and UBA7 in the tumour and respective normal tissue of asbestos-exposed and non-exposed patients were analyzed due to their role at the early stages of protein ubiquitination and ubiquitin-like modification processes." (PMID 19014429, 2008). "We did not detect exposure-related differences in UBA1 or UBA7 levels in the normal or tumour tissue samples." (PMID 19014429, 2008).
cancer (11 papers, 2012 to 2025). A tumor composed of atypical neoplastic, often pleomorphic cells that invade other tissues. "In conclusion, the consistent association between low UBA7 expression and reduced survival across diverse cancer cohorts underscores the importance of UBA7 as a key contributor to cancer progression and patient outcomes." (PMID 40158006, 2025). "Notably, six TCGA cancer cohorts exhibited significant results, showing that patients classified with low UBA7 gene expression profiles have reduced overall survival rates, and this observation was statistically significant." (PMID 40158006, 2025). "Therefore, UBA7 may be an important regulator of anti-cancer and inflammatory responses." (PMID 36771004, 2023). "The UBA7/UBE1L gene was shown to reduce cyclin D1 protein levels, and it possibly affects other pathways via increasing ISGylation, thus having a pronounced anti-proliferation effect in cancer cell lines." (PMID 29088719, 2017). "We were thereby able to show a positive correlation between BTN3A1, MAP3K3, and UBA7 expression and the majority of immune infiltrates (B cells, CD4 + T cells, CD8 + T cells, macrophages, and neutrophils) in most cancer types, and a negative correlation with myeloid dendritic cells." (PMID 39127727, 2024).
hematologic disease (2 papers, 2025). "Additionally, the limited existing research on UBA7 in the context of hematological malignancies and MDS in particular compared to other genes presents a unique opportunity to explore novel regulatory mechanisms and therapeutic targets." (PMID 40158006, 2025).
immune system diseases (1 paper, 2015). "Specifically, eight genes (IRF5, UBA7, TMTC1, GSTM3, FBN2, OAS1, PODXL, ITGA2) were previously associated with immune system diseases in at least one study." (PMID 25874939, 2015).
neurodevelopmental disorder (1 paper, 2026). A behavioral and cognitive disorder with onset during the developmental period that involves impaired or aberrant development of intellectual, motor, or social functions. "Here, we identified individuals with neurodevelopmental disorder phenotypes harboring biallelic UBA7 gene variants and assessed their functional effects." (PMID 42023152, 2026).
UBA7 also shares sentences with these, for which no sentence is quoted: VEXAS syndrome (5 papers); frontotemporal dementia (2); leukemia (2); squamous cell carcinoma (2); uterine corpus endometrial carcinoma (2); acute promyelocytic leukemia (1); adenocarcinoma (1); Alzheimer disease (1); asthma (1); breast tumor (1); COVID-19 (1); emphysema (1); Fanconi anemia (1); gastritis (1); HCMV infection (1); head and neck squamous cell carcinoma (1); hepatocellular carcinoma (1); Listeria infection (1); melanoma (1); myelodysplastic neoplasm (1); ovarian carcinoma (1); ovarian serous cystadenocarcinoma (1); Parkinson disease (1); psoriasis vulgaris (1); Sepsis (1); thyroid cancer (1); uterine carcinosarcoma (1); vasculitis (1).